EGFR (epidermal growth factor receptor)
Diseases named in the same sentence as EGFR in open-access papers (continued):
Sharing a sentence is not in itself a finding about the gene and the disease.
glioblastoma (continued). "The EGFR contributes to the tumorigenic cellular diversity of glioblastoma by participating in the expansion of diverse cell types that initiate tumors." (PMID 24381541, 2013). "The amplification and overexpression of EGFR is found in approximately 50% of glioblastomas and promotes invasion, proliferation and apoptosis arrest." (PMID 24381541, 2013). "Since our in vitro studies demonstrated that miR-219-5p targeted EGFR, we analyzed the correlation between miR-219-5p levels and EGFR protein levels in glioblastoma patient samples." (PMID 23690991, 2013). "EGFR, one of the important upregulated RTKs in glioblastoma, was predicted as a target of miR-219-5p by the target prediction algorithm RNA Hybrid, which proposed binding site for miR-219-5p in the 3′-UTR of EGFR." (PMID 23690991, 2013). "We also found significant negative correlation between miR-219-5p levels and total as well as phosphorylated forms of EGFR in glioblastoma patient samples." (PMID 23690991, 2013). "This indicated that the downregulation of miR-219-5p in glioblastoma patients contribute to the increased activity of the RTK pathway by the upregulation of EGFR." (PMID 23690991, 2013). "EGFR amplification, for example, is a signature genetic event for human glioblastoma, and yet few cell populations derived from human glioblastoma biopsies ever maintain EGFR amplification in culture." (PMID 24349039, 2013). "Approximately 50% of high-grade astrocytomas show EGFR amplification that leads to glioblastoma malignization." (PMID 24381541, 2013). "Our finding that the glioblastoma downregulated miR-219-5p targets EGFR provides insights into the additional mechanisms of deregulation of receptor tyrosine kinases in glioblastoma leading to the aberrant activation of the RTK pathway." (PMID 23690991, 2013). "The hsa-miR-7, which targets EGFR, is a potential tumor suppressor in glioblastoma targeting critical cancer signalling pathways." (PMID 23776563, 2013). "In adults, it has been well appreciated that alterations of EGFR occur in a large fraction of glioblastomas." (PMID 23592488, 2013). "Since most glioblastomas express both wild-type EGFR and EGFRvIII as well as HER2/neu, they are excellent targets for activated T cells (ATC) armed with bispecific antibodies (BiAbs) that target EGFR and HER2." (PMID 23433400, 2013). "It has been shown that elevated levels of EGFR protein and EGFR amplification are present in 40-60% of glioblastomas." (PMID 23594406, 2013). "Chromogenic in situ hybridization showed that PriGO8A cells had three copies of the EGFR gene, likely reflecting a gain of chromosome 7, a characteristic genetic feature of glioblastoma." (PMID 23907540, 2013). "This question was addressed by K.A. Wong and colleagues (Tufts Medical Center, USA), in a mouse model of glioblastoma multiforme, characterised by the over-expression of EGFR and impaired Cdkn2a function." (PMID 26082318, 2013). "As previously assessed, VEGFR and EGFR play a significant role in glioblastoma angiogenesis and proliferation, making tyrosine kinase (TK) receptors logical targets for treatment." (PMID 24294521, 2013). "Expression of the constitutively activated mutant EGFR variant III (EGFRvIII), the most common mutation in glioblastoma multiforme (GBMs), has been clinically correlated with tumor proliferation, invasion, and angiogenesis." (PMID 23617883, 2013). "In 40–50% of glioblastomas EGFR is present at levels several-fold higher compared to the levels in normal cells." (PMID 23724064, 2013). "Some of these alterations, such as del (1p36), del (2p21), +7, del (6q27q29)/−6, EGFR (7p11.2), MDM2 (12q15) and CDK4 (12q14.3) amplification, −10, amplification of 15q24.1, del (17p13)/−17, −19, −22 were known to be associated with glioblastomas." (PMID 23472076, 2013). "Iressa is an EGFR inhibitor that blocks the activity of EGFR and stops cell growth and has been shown to inhibit glioblastoma cell growth." (PMID 23724064, 2013).
glioblastoma (continued). "Another gene in Merged module is ADP-ribosylation factor 4 (ARF4) that activates EGFR signaling has an anti-apoptotic function in human glioblastoma-derived U373MG cells." (PMID 23874428, 2013). "This indicated that miR-219-5p downregulation in glioblastoma leads to the increased levels of EGFR." (PMID 23690991, 2013). "In 3 glioblastomas, rare EGFR-amplified cells (1 cell in 1/10 vessels) were identified attached to the outer aspect of tumor vasculature but not definitively within the wall." (PMID 22298889, 2012). "Recently, miR-7 has been found to reduce EGFR (epidermal growth factor receptor) expression in glioblastoma, breast and prostate cancer cells." (PMID 22876288, 2012). "EGFR is ubiquitously expressed in normal epithelial tissue but is over-expressed in several cancers including lung, glioblastoma, prostrate, breast, colon, ovary and head and neck." (PMID 22359620, 2012). "GNS cells display transcriptional alterations common in glioblastoma, including upregulation of the epidermal growth factor receptor (EGFR) gene and downregulation of the tumor suppressor PTEN." (PMID 23046790, 2012). "The same observation was made in glioblastomas, where expression of PTEN was associated with clinical response to the EGFR kinase inhibitors gefitinib and erlotinib." (PMID 22240798, 2012). "On the other hand, they note that transcriptomic signatures induced by EGFR overexpression mimic those of glioblastoma stem cells." (PMID 23226159, 2012). "The number of CD34+ endothelial cells with extra EGFR copies was similar in glioblastomas with chromosome 7 gain or EGFR amplification and the smaller subset lacking such abnormalities (p=0.8, Fisher Exact Test)." (PMID 22298889, 2012). "We sought to confirm this impression by analyzing vessels in glioblastoma previously examined using chromogenic in situ hybridization (CISH) for EGFR and immunohistochemistry for mutant IDH1." (PMID 22298889, 2012). "Over 80% of glioblastomas have an acquired alteration in the RTK/PI3K/AKT pathway with about 40% of tumors having some alteration in EGFR suggesting that scarcity of a prevalent alteration is not the problem with targeted therapy in most GBMs." (PMID 23056179, 2012). "High frequencies of EGFR overexpression have been reported in head and neck squamous cell carcinomas and glioblastomas." (PMID 22438909, 2012). "To more directly address the contribution of neoplastic cells to vascular endothelium, we concurrently examined EGFR gain and endothelial marker expression in a cohort of 86 glioblastomas on the Johns Hopkins tissue microarrays." (PMID 22298889, 2012). "We also re-reviewed 10 glioblastoma cases from Brigham and Women's Hospital with high level EGFR amplification based on clinical CISH analysis." (PMID 22298889, 2012). "The CN for EGFR was increased in the four glioblastomas with ratios of EGFR to CEP 7 increased to values of more than 20 in at least some cells of each glioblastoma." (PMID 22691727, 2012). "The finding of a high frequency of EGFR amplification provided an explanation to the often occurring double minute chromosomes in glioblastoma; these are known to harbor amplified DNA segments." (PMID 22512247, 2012). "Although several studies have been performed aiming to establish molecular profiles that would predict predictive clinical responses towards EGFR and/or mTOR inhibition, a convincing molecular signature for glioblastoma is still elusive." (PMID 22530122, 2012). "Five moderate to high-level amplified genes in glioblastomas identified in this study, EGFR, PDGFRA, CDK4, MDM2 and CYP27B1, have also been previously reported, sometimes with co-amplification." (PMID 22691727, 2012). "Glioblastomas with EGFR gene amplification expressed significantly stronger EGFRv1, -v2, -v3 and -v4 mRNA levels than gliomas with no EGFR amplification." (PMID 22159595, 2012).
glioblastoma (continued). "Gains of EGFR occurred in 70% of 40 glioblastomas in one study with high levels of gene amplification occurring as double minutes in 42% of the cases." (PMID 22691727, 2012). "Overexpression of wild-type or truncated and constitutively activated EGFR is now considered an important event in the pathogenesis of a subset of glioblastoma." (PMID 22512247, 2012). "Our finding that RhoG contributes to Rac1 activation downstream of EGFR in glioblastoma cells however, contrasts to published observations that EGF-stimulated Rac1 activation is independent of RhoG in HeLa cells." (PMID 22966858, 2012). "Loss of PTEN seems associated with unresponsiveness to targeted therapy against EGFR in colorectal cancer and glioblastomas, moreover it predicts resistance to trastuzumab in HER2-positive breast cancer." (PMID 22240798, 2012). "Our data tend to indicate that the role of EGFR pathway in glioblastoma oncogenesis is more complex than expected." (PMID 22159595, 2012). "This can be further supported by the correlation of p-AKT activation with EGFR gene amplification and with progression from anaplastic astrocytomas to glioblastoma." (PMID 22530122, 2012). "Together with EGFR amplification, the loss of PTEN is the most frequent alteration observed in primary glioblastomas." (PMID 22429330, 2012). "Src inhibition combined with an anti-EGFR monoclonal antibody further inhibited tumor growth and increased survival in an orthotopic glioblastoma mouser model." (PMID 21776389, 2011). "In an independent study on glioblastoma patients, Lu have shown that Src and Fyn act as effectors of oncogenic EGFR signaling and enhance invasion and tumor cell survival in vivo." (PMID 21776389, 2011). "ECOP is co-amplified with EGFR in glioblastoma as well as other cancers, RUNX2 is expressed in glioblastoma cells, and PCDH11X is associated with late-onset Alzheimer's disease." (PMID 21510904, 2011). "Epidermal growth factor receptor (EGFR) signalling is frequently altered during glioblastoma de novo pathogenesis." (PMID 21934682, 2011). "What needs to be added, similar problems were described for EGFR amplification analysis in glioblastomas, that is, disappearance of EGFR amplification was observed in standard cell culture conditions." (PMID 21326241, 2011). "The query results show that the corresponding antibody is EGFR and the most predominant histological type among the samples where EGFR is highly expressed in TMA is glioblastoma according the data in Xperanto-RDF." (PMID 21342584, 2011). "IGF-1R mediates resistance to anti-EGFR therapy in primary glioblastoma through the continued activation of the PI3K/AKT survival pathway." (PMID 21776391, 2011). "Exosomes from glioblastoma patients expressed esRNA for a truncated and oncogenic form of the epidermal growth factor receptor, known as EGFRvIII that can be transferred via exosomes to neighbouring cells." (PMID 21651777, 2011). "The classical subgroup of glioblastoma, as defined by TCGA, was found to have high expression of EGFR and PDGFA." (PMID 21934682, 2011). "Src homology domain-containing phosphatase 2 (SHP2) (PTPN11) is a non-receptor PTP, which regulates several of the RTK pathways known to be overexpressed in glioblastoma, including EGFR, FGFR and PDGFR." (PMID 21934682, 2011). "EGFR over-expression is one of the most common genetic alteration in primary glioblastoma multiforme (GBM) with a frequency of approximately 40%." (PMID 20305783, 2010).
glioblastoma (continued). "EGFR and PTEN gene mutations are likely to play a role in glioblastoma invasion based on the known interaction between EGFR and Focal Adhesion Kinase (FAK) to promote cell migration and the role for PTEN as an inhibitor of cell migration." (PMID 20652056, 2010). "Our genetic and biological data, as well as data from other studies, suggests that ERRFI1 is another key component in the EGFR signaling pathway involved in glioblastoma development." (PMID 21113414, 2010). "Several studies have to a varying degree shown amplification of the EGFR (c-erbB1) gene, located on chromosome 7, in glioblastoma multiforme." (PMID 20331873, 2010). "Epidermal growth factor stimulates vascular endothelial growth factor expression in a panel of EGFR-positive cancer cells, including glioblastoma, gastric cancer, vulvar squamous carcinoma, bladder cancer and prostate cancer." (PMID 20010942, 2010). "As epidermal growth factor (EGF) is a key player in neoplastic progression and AKT is a key effector of EGFR signalling, we analyzed EGFR levels in glioblastoma treated with PF4-DLR." (PMID 21060779, 2010). "Amplification of EGFR gene was shown in half of the glioblastomas, as well as overexpression of EGFR mRNA and protein." (PMID 20487573, 2010). "Amplification of the EGFR gene occurs in up to 50% of human glioblastomas, whereas the reported frequency in anaplastic astrocytomas varies considerably between none to about one third of the cases." (PMID 20331873, 2010). "Gene expression analysis indicated that reduced expression of BER genes in glioblastomas with high EGFR expression correlated with improved patient survival." (PMID 20532243, 2010). "This study was an extension of our research on erb receptor expression in glioblastomas, and was designed to investigate the extent of EGFR gene amplification and overexpression in anaplastic astrocytomas." (PMID 20331873, 2010). "For example, gene amplification and extracellular domain deletions of EGFR are found in 40–60% of glioblastoma multiforme patients." (PMID 20010942, 2010). "Despite the critical role of Epidermal Growth Factor Receptor (EGFR) in glioblastoma pathogenesis, EGFR targeted therapies have achieved limited clinical efficacy." (PMID 20532243, 2010). "TCPTP suppresses the tumorigenicity of glioblastoma cells expressing a mutant epidermal growth factor receptor." (PMID 20698951, 2010). "The epidermal growth factor receptor (HER1/EGFR) is known to be disregulated in a large subgroup of glioblastoma multiforme cases." (PMID 20657384, 2010). "On the contrary an EGFR/GAPDH ratio ≥ 2 was obtained in a grade IV glioblastoma sample, known to have EGFR amplicons, that we used as positive control." (PMID 19196452, 2009). "Future studies will be needed to examine if EGFR amplification and PTEN mutation/10q LOH were enriched in the subgroups of glioblastomas that showed strong TGFβ transcriptional response." (PMID 19192267, 2009). "In Patient 2, an increase was found in the EGFR copy number with its strong expression and PTEN mutation; these are all aberrations found in de novo glioblastoma." (PMID 19830138, 2009). "The molecular genetics of gliosarcoma is fairly similar to that of primary glioblastoma, except for EGFR amplification, which seems to be less frequent." (PMID 19333441, 2009). "Primary glioblastomas exhibit frequent EGFR amplification, homozygous deletion of CDKN2A and p14ARF, CDK4 amplification, MDM2 or MDM4 amplification, RB1 mutation/homozygous deletion, monosomy 10 and PTEN mutation." (PMID 19333441, 2009). "EGFR amplification is particularly frequent in primary glioblastomas with a small cell, highly anaplastic histological phenotype." (PMID 19333441, 2009). "Amplification of EGFR or MDM2, PTEN mutation as well as homozygous CDKN2A or p14ARF deletions are all rare in secondary glioblastomas." (PMID 19333441, 2009). "EGFR amplification and PTEN mutations/10q LOH are frequent genetic alterations observed in glioblastomas." (PMID 19192267, 2009).
glioblastoma (continued). "In this regard, glioblastoma cells overexpressing EGFR, but resistant to inhibition by EGFR kinase inhibitors, were sensitive to HSP90 inhibition." (PMID 18320023, 2008). "These gliomas harbored a gene expression profile that partially resembled the gene expression of normal brain samples, whereas gliomas with EGFR amplification expressed many genes in common with glioblastoma cancer stem cells." (PMID 18492260, 2008). "EGFR amplification is more frequent in glioblastomas, but it is also found in a subset of anaplastic oligodendrogliomas and, in this setting, is predictive of extremely poor prognosis." (PMID 18492260, 2008). "Gliomas with EGFR amplification and glioblastoma cancer stem cells were both characterized by a large gene cluster (G) most significantly enriched in genes involved in proliferation (34 genes, p < 10-4) and in CNS development (16 genes, p < 10-4)." (PMID 18492260, 2008). "EGFR is frequently amplified in glioblastomas and 30 to 40% of glioblastomas also express the deletion mutation EGFRvIII." (PMID 17437646, 2007). "In aggressive tumors, such as glioblastomas, some studies have shown that EGFR gene amplification is correlated to shorter survival time and resistance to radiotherapy." (PMID 19455247, 2007). "Studies of glioblastomas and EGFR have focused on the effects EGFRvIII has in up-regulating the PI3K/Akt pathway as the mechanism behind the tumorigenicity of EGFRvIII." (PMID 17437646, 2007). "Targeting EGFR in glioblastomas has the additional challenge of the expression of EGFRvIII (epidermal growth factor receptor variant type III; also named de2-7 EGFR and deltaEGFR)." (PMID 17437646, 2007). "For future work it would be useful to test NSC-154829 in combination with known EGFR inhibitors and/or proven glioblastoma therapies such as radiation." (PMID 17437646, 2007). "Glioblastomas with EGFR amplifications frequently carry an intragenic deletion of exons 2 through 7, resulting in expression of the constitutively active EGFRvIII isoform." (PMID 18688287, 2007). "Percentage of reported EGFR-amplification/overexpression in patients with glioblastoma multiforme: Literature overview." (PMID 16709245, 2006). "Antisense-epidermal growth factor receptor approach was used to inhibit epidermal growth factor receptor expression of glioblastoma U87MG cells." (PMID 11953893, 2002). "The antisense-EGFR constructs were transfected into a glioblastoma cell line U87MG and stable transfected clones were isolated." (PMID 11953893, 2002). "In the present study we demonstrated that epidermal growth factor receptor is involved in regulation of telomerase activity in glioblastoma." (PMID 11953893, 2002). "In glioblastoma, EGFR is found to be overexpressed and /or amplified in up to 50% of all cases, suggesting an important role of this gene in glial tumorigenesis and progression." (PMID 11953893, 2002). "The use of antisense-EGFR RNA to block the function of enhanced EGFR in human glioblastoma cells has been reported to inhibit cellular proliferation and induce differentiation." (PMID 11953893, 2002). "Epidermal growth factor receptor is overexpressed and/or amplified in up to 50% of glioblastomas, suggesting an important role of this gene in glial tumorigenesis and progression." (PMID 11953893, 2002). "This review highlights recent studies of how lipids regulate EGFR activity, with special attention paid to potentially actionable co-dependent lipid metabolism in glioblastoma multiforme and promising new methods for studying membrane protein-bilayer interactions." (PMID 41569525, 2026). "Glioblastoma (GBM) heterogeneity limits the efficacy of EGFR-targeted therapies." (PMID 42087893, 2026).